YTHDF1 (YTH N6-methyladenosine RNA binding protein F1)
Diseases named in the same sentence as YTHDF1 in open-access papers (continued):
Sharing a sentence is not in itself a finding about the gene and the disease.
tumor (continued). "Furthermore, in mouse syngeneic tumor models, Ythdf1 depletion in cancer cells resulted in reduced tumor growth and increased tumor‐infiltrating lymphocytes, which are attributed to the augmentation of IFN‐γ signaling." (PMID 39587835, 2025). "In addition, we provided evidence showing that YTHDF1 or RNF7 depletion sensitizes tumor cells to chemotherapy drug cisplatin by increasing cellular apoptosis." (PMID 40251202, 2025). "Numerous studies support the notion that YTHDF1 promotes tumor growth while suppressing apoptosis." (PMID 39821576, 2025). "YTHDF1 specifically recognizes and binds to m6A modifications on RNA, influencing the stability and translation of target transcripts involved in immune evasion and tumor progression." (PMID 39911396, 2025). "Moreover, YTHDF1 depletion decreased cell proliferation, migration, and xenograft tumor formation capacity." (PMID 40251202, 2025). "In YTHDF1 knockdown tumor cells, only RNF7 (RING Finger protein 7), also known as SAG (Sensitive to Apoptosis Gene), a crucial subunit of the RBX/ROC RING of E3 ubiquitin ligase essential for cancer cell growth, was significantly reduced compared to control cells." (PMID 40251202, 2025). "Translationally, in vivo targeting of YTHDF1 via VNP-encapsulated siYTHDF1 or salvianolic acid C inhibited tumor growth (P < 0.05 for both treatments) and increased treatment efficacy when VNP was combined with oxaliplatin (P < 0.05, SAC: P < 0.01) or 5-fluorouracil (P < 0.05 for both treatments)." (PMID 41423446, 2025). "By inhibiting YTHDF1, it may be possible to reverse immune suppression within the tumor microenvironment, enhance immune cell activation, and improve the efficacy of immunotherapies." (PMID 39911396, 2025). "Silencing YTHDF1 combined with anti-PD-1 therapy significantly inhibits tumor progression." (PMID 40034695, 2025). "The m6A reader protein YTHDF1 plays a key role in reducing MHC I expression in tumor cells." (PMID 40176140, 2025). "YTHDF1 exhibits elevated expression in GC, which facilitates the progression of this malignancy by influencing cellular proliferation and the immune response within the tumor microenvironment." (PMID 41584846, 2025). "Interestingly, tumour‐intrinsic YTHDF1 promotes immune evasion and ICB resistance by enhancing lysosomal proteolysis of MHC‐I and antigens, thereby impairing immune surveillance." (PMID 40673641, 2025). "Furthermore, depletion of Ythdf1 leads to decreased tumor growth and enhanced infiltration of immune cells in a mouse syngeneic tumor model." (PMID 39587835, 2025). "On the delivery front, immune-cell-targeted nanoparticles (e.g., TAM/DC-directed carriers for YTHDF1 siRNA) and tumor-tropic ligands enable compartment-specific epitranscriptome editing while sparing non-target tissues—critical given widespread physiologic roles of RNA-modification enzymes." (PMID 41280938, 2025). "Importantly, YTHDF1 within dendritic cells is capable of recognizing m6A-modified transcripts of lysosomal proteases, and its knockout abolishes the tumor antigen cross-presentation capacity of classical dendritic cells." (PMID 40986143, 2025). "Modulation of YTHDF1 or YTHDF2 activity could reshape the tumor immune microenvironment by influencing antigen presentation, cytokine production, and immune cell infiltration." (PMID 41403953, 2025). "Moreover, the role of YTHDF1 in regulating anti-tumor immunity has recently gained significant attention." (PMID 40739089, 2025). "For instance, YTHDF1, an m6A reader protein, collaborates with other m6A-specific mRNA binding and translation proteins to regulate the methylation and expression of HIF genes, thereby promoting hypoxia-associated tumor progression." (PMID 38902779, 2024). "Moreover, YTHDF1 plays an important role in the tumor microenvironment (TME), and YTHDF1 knockdown increases antigen-specific CD8 + T cell anti-tumor effects." (PMID 38166832, 2024).
tumor (continued). "Indeed, the IR and anti–PD-L1 combination resulted in almost complete tumor regression in mice treated with Ythdf1-KO DC vaccines." (PMID 39325547, 2024). "These associations might also coincide with a higher tumor mutational burden (TMB) score, suggesting that patients with elevated YTHDF1 levels could potentially derive greater benefits from immunotherapy." (PMID 39199429, 2024). "We then validated YTHDF1 expression via IHC staining of the harvested tumours." (PMID 38683130, 2024). "Collectively, this study reveals that YTHDF1 may serve as a promising anti-tumor candidate for developing an understanding of antitumor immunity through m6A regulation." (PMID 39557826, 2024). "Subsequently, to test whether YTHDF1 regulated the immunosuppressive tumor microenvironment, the immunosuppressive cytokines (IL-10, TGF-β) and immune effector cytokines (IFN-γ, IL-2) were tested." (PMID 39557826, 2024). "However, almost all subsets of tumour‐infiltrating lymphocytes including CD8+ T cells are high in high YTHDF1 and YTHDF2 lung cancers, suggesting distinct downstream target genes of m6A readers between cancer types." (PMID 38545841, 2024). "Furthermore, depletion of the m6A-specific reader YTHDF1 in combination with PD-1 blockade has shown enhanced efficacy in anti-tumor therapy." (PMID 38902779, 2024). "Therefore, we analyzed the correlation between YTHDF1 expression and six types of tumor-infiltrating immune cells (TIICs) in the TIMER database." (PMID 38339157, 2024). "Administration of cells overexpressing YTHDF1 increased tumour volumes when compared with Vector group (p < 0.0001), while cells knocking‐down YTHDF1 (shYTHDF1‐1, p < 0.0001 and shYTHDF1‐2, p < 0.0001) decreased tumour volumes when compared with shControl group in the xenograft model." (PMID 38683130, 2024). "The findings revealed that YTHDF1 had a favorable relationship with tumor purity and these TIICs." (PMID 38339157, 2024). "Indeed, using flow cytometry, we observed a higher level of PD-L1 in tumor-infiltrating DCs from Ythdf1-cKO+IR mice compared with those from WT mice." (PMID 39325547, 2024). "Moreover, compared with WT-BMDCs, Ythdf1-cKO BMDCs exhibited a significantly higher levels of IFN-β production when cocultured with irradiated tumor cells (P < 0.001)." (PMID 39325547, 2024). "Importantly, two strategies improved tumor control: in vivo cathepsin inhibition combined with RT, as well as Ythdf1 deletion or inhibition in tumor antigen–loaded DC vaccines delivered to mice receiving RT." (PMID 39621308, 2024). "Thus, YTHDF1 promotes the progression of GC by upregulating DNMT3B, and inhibiting DNMT3B contributes to reduce the tumor promotion ability of YTHDF1." (PMID 39185313, 2024). "Moreover, transcriptome analyses of matched GBC tissues from our cohort and an external dataset revealed YTHDF1 overexpression in the tumour tissues." (PMID 38683130, 2024). "Similarly, YTHDF1/YTHDF3 has been implicated in increasing the translational efficiency of Integrin Subunit Alpha 1 (ITGA), one of the genes that are defined as “tumor differentiation signature”, through the recognition of the m6A site present on its 3′UTR." (PMID 39342406, 2024). "In addition, YTHDF1 inhibits the function of anti-tumor immune cells in the tumor microenvironment (TME) by influencing the degree of the infiltration of CD8+ T cells and natural killer cells." (PMID 38339157, 2024). "Interestingly, in CRC, YTHDF1 promotes cancer cell proliferation and metastasis, and enhancing YTHDF1 expression inhibits tumor sensitivity to cisplatin." (PMID 39033180, 2024). "Moreover, an ex vivo assay with cocultured bone marrow–derived DCs (BMDCs) and B16-OZ cells showed that irradiated tumor cells had increased YTHDF1 expression at both mRNA and protein levels." (PMID 39325547, 2024). "Moreover, METTL3-mediated methylation of HINT2 mRNA at 3′ and 5′UTR regions, known for its tumor suppressor functions, facilitates the binding of YTHDF1 to promote its translation." (PMID 38444581, 2024).
tumor (continued). "Plasmids expressing short hairpin RNA (shRNA) against Ythdf1 (shY1, downregulating Ythdf1 expression) and liposome-modified tumor cells membrane (CM) would be packaged and squeezed through a polymeric membrane in an extruder to form shY1-CM nanoparticles as a Ythdf1-targeted biomimetic nanovaccine." (PMID 38534224, 2024). "IGF2BP2 and YTHDF1 exerted oncogenic effects on tumor growth and apoptosis inhibition." (PMID 37612282, 2023). "In addition, the expression of YTHDF1 increased with increasing tumor grade in the GSE13507 and TCGA databases." (PMID 37108067, 2023). "Collectively, this study found that YY1 was regulated by ALKBH5 and YTHDF1-mediated m6A modification and served as an autophagy-dependent tumor driver to accelerate cancer progression through ATG4B transactivation, providing an exploitable therapeutic target for GC." (PMID 37724907, 2023). "To further investigate our hypothesis, we initially performed transcriptome analysis to screen the differential biological processes and pathways between Ythdf1-KO and WT tumor tissues in immunocompetent mice." (PMID 36650153, 2023). "Notably, the elevation of HIF-1α levels in hypoxic tumor cells suppresses the expression of miR-16-5p, facilitating the recruitment of YTHDF1 and its subsequent binding to the pivotal enzyme PKM2 mRNA within glycolysis." (PMID 38202722, 2023). "Interestingly, tumor-intrinsic YTHDF1 deficiency significantly inhibited tumorigenesis in immunocompetent mice, as evidenced by a lower tumor volume, tumor weight, and luminescence intensity and a favorable survival time in the Ythdf1-KO group." (PMID 36650153, 2023). "Moreover, they found higher expression levels of NK cells and CD8+ cytotoxic T cells in the tumors of YTHDF1 knockout mice than WT mice, suggesting a stronger anti-tumor response when YTHDF1 is present." (PMID 37019148, 2023). "Additionally, hypoxia-mediated downregulation of miR-16-5p restored YTHDF1 expression, thereby promoting tumor glycolysis by enhancing PKM2 mRNA translation." (PMID 36999016, 2023). "The focus of research on YTHDF1 has shifted in recent years from its m6A-recognition and -modification function to the molecular mechanisms by which it regulates tumor progression, particularly by exploring the regulatory factors that interact with YTHDF1 upstream and downstream." (PMID 38202722, 2023). "YTHDF1 affected immune contexture and potentially promoted tumor progression in patients with COAD." (PMID 36707507, 2023). "Intriguingly, cell-intrinsic N6-methyladenosine reader protein (YTHDF1) in tumors can disrupt tumor antigens and impair immune surveillance, whereas engineered exosomes can be utilized to deliver CRISPR/Cas9 in order to specifically target tumor YTHDF1, thereby, restoring tumor immune surveillance." (PMID 37408250, 2023). "More excitingly, mice cured by YTHDF1 deficiency and ICI exhibited resistance to WT tumor rechallenge, indicating that this combination therapy could elicit effective and long-lasting immune memory that protected the mice from tumor relapse." (PMID 36650153, 2023). "The results showed that the tumor volume decreased significantly after YTHDF1 or TRIM68 knockdown, while overexpression of TRIM68 on the basis of YTHDF1 knockdown could promote tumor growth." (PMID 38042806, 2023). "In addition, the anti-tumor effect of PD-L1 blockade was enhanced in the YTHDF1-/- tumor-bearing mouse models." (PMID 36612317, 2023). "As expected, the expression of FTH showed similar upregulation with YTHDF1 in lung tumor tissues compared with para-tumor tissues, which confirmed that inhibition of YTHDF1 could suppress FTH activity." (PMID 37259333, 2023). "Indeed, an anti-PD-L1 or anti-CTLA-4 antibody remarkably reduced tumor volume in mice bearing Ythdf1-KO B16/F10 cells compared with an immunoglobulin G (IgG) antibody." (PMID 36650153, 2023). "For example, YTHDF1 regulated tumor progression and CSC-like characteristic in CRC." (PMID 36707507, 2023).
tumor (continued). "Furthermore, experimental results have shown that combining YTHDF1 knockout with anti-PD-1 immune checkpoint inhibitor therapy significantly improves treatment efficacy and reduces the tumor’s resistance to immune checkpoint inhibitors." (PMID 38202722, 2023). "CAFs are important constituents of the tumor microenvironment, and YTHDF1 may be involved in their functions." (PMID 38202722, 2023). "However, in ocular melanoma, YTHDF1, as a tumor suppressor, promotes the translation of HINT2 mRNA (a tumor suppressor) containing m6A." (PMID 37437245, 2023). "Furthermore, it has been confirmed that elevated YTHDF1 expression is correlated with various malignant tumor behaviors, including invasiveness, and lymph node metastasis." (PMID 36650570, 2023). "In addition, YTHDF1 promotes tumor progression in CRC by promoting ARHGEF2 translation and RhoA signaling." (PMID 37063421, 2023). "Indeed, flow cytometry validated that tumor-infiltrating CD4+ T cells from the Ythdf1-KO group exhibited strong production of IFN-γ and granzyme B." (PMID 36650153, 2023). "Based on our results showing that tumor-intrinsic YTHDF1 contributes to immune evasion and is associated with ICI resistance, we explored whether YTHDF1 deficiency improves the efficacy of ICI therapy in mouse models." (PMID 36650153, 2023). "Mechanistically, YTHDF1 deficiency inhibits the translation of lysosomal genes and limits lysosomal proteolysis of the major histocompatibility complex class I (MHC-I) and antigens, ultimately restoring tumor immune surveillance." (PMID 36650153, 2023). "Here, we hypothesized that Ythdf1 KO limited lysosomal proteolysis in tumor cells, ultimately enhancing the MHC-I expression and minimizing the destruction of internalized antigens." (PMID 36650153, 2023). "Directly targeting and knocking out YTHDF1 can also restore anti-tumor immune activity." (PMID 38202722, 2023). "However, there is a paucity of comprehensive reviews examining the mechanistic role of YTHDF1 in tumor cell metabolic reprogramming." (PMID 38202722, 2023). "As miR‐346 decreased, accumulating YTHDF1 promoted tumour growth and indicated a poor prognosis." (PMID 36162823, 2023). "The specificity and sensitivity of YTHDF1 in various tumor models were more than 0.800." (PMID 36707507, 2023). "Furthermore, a mounting body of research indicates that YTHDF1 not only plays a pivotal role in protein translation and biological growth processes, but also exerts critical influence within tumor cells." (PMID 38202722, 2023). "Moreover, the heightened expression of YTHDF1 exerts a tangible impact on tumor cells during therapeutic interventions." (PMID 38202722, 2023). "On the contrary, anti‐tumour miR‐376c targeted oncogenic YTHDF1 in NSCLC." (PMID 36162823, 2023). "Furthermore, we summarize the latest pathological and physiological processes involving YTHDF1 in tumor cells, and analyze potential therapeutic approaches that utilize YTHDF1." (PMID 38202722, 2023). "ROC curve showed that YTHDF1 expression was accurate in predicting ESCA tumor outcome." (PMID 35401696, 2022). "In addition, the therapeutic efficacy of PD-L1 checkpoint blockade immunotherapy is greater in Ythdf1–/– mice than wild-type mice, thus indicating that YTHDF1 is a potential therapeutic target in anti-tumor immunotherapy." (PMID 35254013, 2022). "In addition, in vitro experiments revealed that blocking YTHDF1 improved the therapeutic effect of anti-PD-L1 in GC cells, and the knockout of m6A demethylase AlKBH5 makes tumor sensitive to anti PD-1 immunotherapy and changes immune cell recruitment." (PMID 36561529, 2022). "have demonstrated that YTHDF1 is an essential mediator of tumor immune evasion; their findings suggest that it may be a potential target for improving the efficacy of immunotherapy." (PMID 35185897, 2022). "We investigated the effect of down regulation of YTHDF1 on OS tumor growth." (PMID 35156522, 2022).
tumor (continued). "YTHDF1 also exerts a pro-tumorigenic effect by altering the tumor microenvironment." (PMID 35884552, 2022). "Moreover, the deletion of YTHDF1 enhances the cross-presentation of tumor antigens and the cross initiation of CD8+T cells in vivo." (PMID 35311150, 2022). "For instance, ALKBH5 regulated Tregs and MDSC accumulation via modulating the expression of Mct4/Slc16a3; FTO facilitated immune invasion and desensitized tumor cells to T cell cytotoxicity; YTHDF1 was correlated with immune cell infiltration but attenuated DCs' cross-presentation capacity." (PMID 35936362, 2022). "Additionally, in vivo tumor growth and metastasis experimental assays were performed to evaluate the role of YTHDF1 in tumorigenesis." (PMID 36439881, 2022). "Furthermore, in a melanoma cancer model, the frequency of tumor regression to anti-PD-L1-treatment was increased in YTHDF1 knockout mice than in wild-type mice." (PMID 36479088, 2022). "Overexpression of YTHDF1 enhanced the stability of RNA lysosomal proteases, which led to the degradation of tumor antigens in dendritic cells, disabled CD8+ T cells to bring about immunosurveillance and abolished the effect of immune checkpoint inhibitors (ICIs)." (PMID 35646049, 2022). "Additionally, YTHDF1 was found to rewire tumor metabolism by promoting the protein translation of glutaminase 1 (GLS1) by targeting the 3′UTR of GLS1 mRNA, which contributes to chemoresistance to cisplatin." (PMID 35884552, 2022). "Low YTHDF1 or YTHDF2 reflects an immune hot tumor signature and may serve as a predictor or prognostic marker." (PMID 36479088, 2022). "The differential roles of YTHDF1 between HCC tumor cells and HSCs may thus confer disparate outcomes for HCC development." (PMID 35884552, 2022). "To uncover the potential mechanism of YTHDF1 in BC, we first determined the differential expression of YTHDF1 in BC and adjacent normal tissue through a honeycomb diagram and found that YTHDF1 was highly expressed in tumour tissues." (PMID 35075167, 2022). "This study shows that the reader protein YTHDF1 may regulate tumor lipid metabolism by reducing the translation efficiency of the target gene HSD17B11." (PMID 35568876, 2022). "Loss of YTHDF1 mediated the overexpression of IFN-γ receptor 1 and JAK/STAT1 signaling pathway in tumor cells, which might contribute to restored sensitivity to antitumor immunity." (PMID 35193930, 2022). "The expression of YTHDF1 has some accuracy in predicting the tumor outcome." (PMID 35401696, 2022). "Gene set enrichment analysis revealed that low YTHDF1 was related to immune hot tumor gene sets." (PMID 36479088, 2022). "Compared with untreated Ythdf1−/− mice or anti-PD-L1-treated WT mice, Ythdf1−/−- mice treated with PD-L1 checkpoint blockade immunotherapy have been found to show more complete tumor regression, thus suggesting YTHDF1 as a potential target in anti-tumor immunotherapy." (PMID 35254013, 2022). "In NSCLC, the expression of YTHDF1 is higher in tumor tissues than in normal tissues, while the expression of YTHDF2 is lower in tumor tissues than in normal tissues, indicating that YTHDF1 is more likely to bind to methylated YAP1 mRNA to promote its translation." (PMID 35063010, 2022). "It is worth noting that some studies have shown that YTHDF1 inhibits tumor progression." (PMID 36017491, 2022). "Loss of YTHDF1 mediated overexpression of interferon (IFN)-γ receptor 1 (IFNGR1) and JAK/STAT1 signaling pathway in tumor cells, which might contribute to restored sensitivity to anti-tumor immunity." (PMID 35193930, 2022). "Moreover, the protein level of YTHDF1 in OS tumor tissues and adjacent tissues was measured through Western blot experiment." (PMID 35156522, 2022). "Knockdown of YTHDF1 could improve the crosspresentation ability of dendritic cells in mouse melanoma, and when combined with a PD-L1 checkpoint inhibitor, the tumor was almost completely controlled." (PMID 36017491, 2022).